MET (MET proto-oncogene, receptor tyrosine kinase)
Diseases named in the same sentence as MET in open-access papers (continued):
Sharing a sentence is not in itself a finding about the gene and the disease.
tumor (continued). "KRAS or MET mutations were also associated with higher TMB, indicating that mutations in these genes may promote tumor immunogenicity in NSCLC." (PMID 38394518, 2024). "Furthermore, the HGF/c-MET pathway stimulates angiogenesis, ensuring an adequate blood and nutrient supply to the tumor, thus fostering further growth and expansion." (PMID 39201787, 2024). "Also, MET inhibition significantly reduced the tumour weight in a xenograft model with RMG1 cells and a PDX model with OCCC compared to controls." (PMID 38030594, 2024). "Additionally, the molecular mechanism underlying its anti-tumor effects was elucidated using phospho-RTK antibody arrays, confirming its ability to inhibit the phosphorylation of MET and VEGFR2 along with activation of downstream signaling pathways." (PMID 38596618, 2024). "Also, c-MET inhibition reduced neutrophil recruitment into T cell–inflamed tumor microenvironment and draining lymph nodes in response to cytotoxic immunotherapies." (PMID 38909206, 2024). "Repeat tumor biopsies may also be particularly important given the observation in the TATTON study that relying on ctDNA mediated assessment of MET amplification may result in a high level of false negatives." (PMID 38276867, 2024). "Future studies could include long-term treatment of polysomy tumor PDXs with osimertinib to evaluate subclonal changes in MET activation, as well as exploration of additional combined targeted therapies for drug resistance." (PMID 38276867, 2024). "Previously, we explored (both in vitro and in vivo) whether tepotinib suppressed the activation of downstream signaling pathways, GC proliferation, apoptosis, MET, and tumor progression." (PMID 38339049, 2024). "The emergence of resistance is also inevitable, as tumor cells may evade CAR-T or CAR-NK cell attacks by downregulating or completely losing MET expression." (PMID 39201787, 2024). "In contrast, TT causes S985 phosphorylation and degradation of p-Y1003 MET, loss of full-length p-Y1234/5 MET, as well as MET-ECD release and this may explain in part why TT caused cancer regression in certain in vivo tumour models." (PMID 38891113, 2024). "Subsequent investigations revealed that tumors with MET amplification displayed reduced levels of STING and less infiltration of CTLs and NK cells, and decreased tumor immunogenicity of the MET-amplified tumor microenvironment was confirmed by single-cell RNA sequencing." (PMID 39201787, 2024). "Furthermore, c-MET inhibition can affect various immune components within the tumor microenvironment, including TANs, TAMs, and Tregs." (PMID 39664377, 2024). "Intriguingly, AZD9592 in vitro efficacy was most robust when both EGFR and c-MET were engaged, suggesting that bispecific targeting of EGFR and c-MET may increase tumor selectivity and reduce on-target toxicities." (PMID 39065587, 2024). "Furthermore, anti-angiogenic therapies, which block VEGF signaling in tumor blood vessels, exacerbate tumor hypoxia, a condition of low oxygen levels that upregulates MET and activates MET-dependent invasive growth in cancer cells." (PMID 39769452, 2024). "Similarly, samples in cluster C2 displayed higher expression in multiple tumor-associated physiological pathways including AKT, EGF, HER2, MAPK, MET, mTOR, PTEN, RAS, WNT and NOTCH signal pathway." (PMID 38434969, 2024). "However, extensive analyses of the TCGA tumor database have revealed new hybrid proteins, where the intracellular domain of MET, or even the full-length MET, is fused with various partners." (PMID 38675409, 2024). "A tumour cell line displaying MET exon 14 skipping has also been employed." (PMID 38652103, 2024). "Thus, FASN inhibition provides an avenue by which pro-tumor effects of both MET and EGFR can be targeted." (PMID 39062731, 2024). "HPV16 E5 may increase MET levels, a growth factor receptor critical for tumor cell invasion, motility, and cancer metastasis." (PMID 39228892, 2024).
tumor (continued). "Furthermore, the expression levels of autophagy-related markers (LC3 and LAMP1) were more increased in non-tumor tissues than in liver tumor tissues, but the expression levels of mTOR and MET were decreased in non-tumor tissues." (PMID 39519229, 2024). "Additionally, HGF/c-MET signaling promotes the migration and invasive capabilities of tumor cells, facilitating local invasion and distant metastasis." (PMID 39201787, 2024). "Notably, the prodrug exhibited excellent stability in serum and effectively suppressed c-MET phosphorylation and tumor cell proliferation in vivo." (PMID 39144632, 2024). "However, the TM00219 PDX tumors displayed significantly lower levels of MET expression and negligible levels of P-MET expression in naïve tumor and in arms treated with osimertinib or osimertinib plus H3 for 13 days." (PMID 39041204, 2024). "The infiltration of TAMs and immune cells thus represents a double-sided sword and on the one hand is associated with an effective response to immune checkpoint inhibitors, but on the other hand can support the growth of MET-expressing tumor cells via secreted factors such as HGF." (PMID 38386085, 2024). "Biologically, METex14 could lead to trans-activation of multiple intracellular signaling pathways including RAS-MAPK43, SMAD244 resulting tumor progression and resistant to MET-targeted therapies." (PMID 39060379, 2024). "Thus, these aberrant fusions of the MET gene act as a “driver” for the activation of the MET protein and downstream signaling pathways, endowing tumor cells with HGF-independent self-activation ability." (PMID 38195556, 2024). "However, the precise role of the HGF/c-MET signaling pathway within the tumor immune microenvironment remains incompletely understood." (PMID 39201787, 2024). "Additionally, a comprehensive exploration of MET signaling’s role within the immune system and its effects on anti-tumor immune responses is imperative." (PMID 39201787, 2024). "c-MET-driven HGF secretion recruits myeloid-derived suppressor cells (MDSCs) and tumor-associated macrophages (TAMs), while TGF-β induces fibroblasts to differentiate into cancer-associated fibroblasts (CAFs), creating a barrier against immune cell infiltration." (PMID 39664377, 2024). "Additionally, neutrophils and macrophages in the TME also contribute to HGF production, further supporting tumor growth through MET activation." (PMID 39598385, 2024). "Furthermore, we suggest interferon-induced expression of HGF in tumor cells triggered by interferon-gamma provided by stromal cells mediates autocrine activation of MET-signaling in tumor cells." (PMID 38386085, 2024). "TT may potentially suppress this evasion strategy in cells expressing wild-type MET, while tumours expressing exon 14 MET deletion mutants may be resistant to TT treatment, and this will require further analysis using exon 14 MET mutant cells." (PMID 38891113, 2024). "Therefore, IL-32γ overexpression induced autophagy in liver tumors through the suppression of MET and mTOR pathways critical for tumor growth inhibition." (PMID 39519229, 2024). "Reduced levels of miR-34a were reported by northern blot in three tumor tissues compared to normal ones; miR-34a negatively regulated cell proliferation and migration by targeting MET (MET proto-oncogene, receptor tyrosine kinase) and affecting the AKT pathway." (PMID 36765733, 2023). "Activation of MET phosphorylates transduction cascade may promote tumor growth, angiogenesis, migration of the cells and metastasis." (PMID 37240178, 2023).
tumor (continued). "In addition, many well-characterized tumor-promoting proteins, including those with roles in metastasis, were increased on the cell surface, including c-MET, EGFR, VEGFR, ALK and ITGα5." (PMID 36674782, 2023). "Our results suggest that tumours bearing METex14 mutation, on its own with no other genetic alteration, will likely display response to MET‐targeted therapies if HGF is both present and accessible to the cancer cells." (PMID 36799689, 2023). "Next-generation sequencing (NGS) of the tumor showed an actionable BRAF V600E mutation and MET N375S mutation of germline origin with unknown actionability while immunohistochemistry testing revealed IDH 1/2 were wild-type." (PMID 37231247, 2023). "Especially in anaplastic, diffuse and PA, c-MET levels often correlate with tumor grade." (PMID 36839989, 2023). "Furthermore, like HER2, MET shows intratumoral heterogeneity: amplified and unamplified tumor cell clones occur in the same tumor distinguishable on a cell-by-cell level, further compromising its usage as a predictive biomarker." (PMID 36260159, 2023). "Since FOXM1‐KO markedly inhibited cell proliferation, decreased expression of FOXM1 may be an important factor in suppressed cell proliferation and tumor growth of HER3/MET‐dKO cells." (PMID 36751113, 2023). "Thus, synergy of irradiation and MET inhibition appears to require an intact immune system and MET expression in the tumor." (PMID 36915128, 2023). "Driver and drug-resistant mutations in primary tumours with LM included: EGFR L858R (10, 35.7%), EGFR 19del (6, 21.4%), EGFR L858R+MET (1, 3.6%), EGFR L858R+S768I (1, 3.6%), ALK (2, 7.1%), ROS1 (1, 3.6%), negative (5, 17.9%), and unknown (2, 7.1%)." (PMID 38269023, 2023). "Adjacent paraffin-embedded tumor sections were stained with c-MET/AF488, cMBP-ICG, and DAPI." (PMID 36184713, 2023). "While some tumor cells are capable of producing HGF and its splice variants, thereby modulating tumor progression through autocrine and paracrine signaling, stromal-derived HGF remains an indispensable element for the sustained activation of c-MET." (PMID 37919751, 2023). "Moreover, we establish a circMET-based molecular annotation to verify that circMET expression reflects the status of MET activity in both cell lines and tumor specimens." (PMID 37170152, 2023). "The Kyoto Encyclopedia of Genes and Genomes (KEGG) analysis revealed that the upregulated genes were enriched in tumor-associated pathways, including pathways in cancer, focal adhesion, ECM–receptor interaction, and cell cycle, in c-MET/sgp53 HCCs versus normal livers." (PMID 37500626, 2023). "METex14 single alteration was sufficient but required HGF to drive MET‐dependent sustained phosphorylation and signalling, enhanced cell motility, anchorage‐independent survival, changes in gene expression and in vivo tumorigenesis in humanised HGF knock‐in mice, sensitising tumours to MET‐TKIs." (PMID 36799689, 2023). "The pleiotropic physiological functions of MET explain its diverse role in cancer progression in a broad range of tumors; genetic/epigenetic alterations of MET drive tumor cell dissemination, metastasis, and acquired resistance to conventional and targeted therapies." (PMID 37760640, 2023). "In this way, we exclusively evaluated the relevance of the HGF/MET axis in prompting cell-autonomous activities (MET signaling in tumor microenvironment cells is maintained intact) independently of their intrinsic ability to proliferate (that is sustained by different oncogenic drivers)." (PMID 37345079, 2023). "Using CRISPR/Cas9, we developed a METex14/WT isogenic model in nontransformed human lung cells and report that the METex14 single alteration was sufficient to drive MET‐dependent in vitro anchorage‐independent survival and motility and in vivo tumorigenesis, sensitising tumours to MET‐TKIs." (PMID 36799689, 2023).
tumor (continued). "Notably, several studies have shown that the pharmacological targeting of MET is associated with the formation of DSBs and impairs DNA repair, synergistically enhancing the radiosensitivity of MET-addicted tumor cells." (PMID 37188738, 2023). "The MET proteins, in turn, activate various proteins such as survivin, the X‐linked inhibitor of apoptosis protein, and other inhibitory apoptotic proteins through the AKT pathway, leading to tumor infiltration and distant metastasis." (PMID 38077251, 2023). "In late 1990s, M. Park’s group discovered an alternatively spliced MET transcript variant, highly expressed in tumor cells, lacking the ATG-containing exon 2 and failing to produce any detectable protein product in vivo." (PMID 37170152, 2023). "Adjuvant treatment with MET inhibitors after tumor resection with curative intent could be a viable strategy." (PMID 37760640, 2023). "Moreover, c-MET/sgp53 tumor lesions exhibited phosphorylation/activation of the ERK signaling (p-ERK)." (PMID 37500626, 2023). "Moreover, both TERT deficiency and dysfunctional telomeres decreased lung tumor implantation and expression of the tumor progression markers Mmp9, Egfr, Hmox1 and c-MET." (PMID 37085672, 2023). "PCR results indicated strong MET staining ( 3+) in more than 50% of tumor cells." (PMID 37400762, 2023). "Undoubtedly, targeting both HGF/c-MET and Hh pathways may produce a more desirable effect, considering the interplay between these two pathways in tumor cells and CAFs, as well as the cross-talk and autocrine mechanisms within cells." (PMID 37919751, 2023). "MET-CAR-T cells derived from healthy subjects (HS) and HCC patients were evaluated for their killing activity and cytokine release against HCC cells with various MET activations in vitro, and for their tumor growth inhibition in orthotopic xenograft models in vivo." (PMID 37779207, 2023). "Taken together, our results suggest that both CD4+ and CD8+ subtypes of MET-CAR-T cells can be responsible for the anti-tumor efficacy, and that CD4+ MET-CAR-T cells may elicit more robust effector T cell functions when applied to clinical settings." (PMID 37779207, 2023). "In this context, MET could be one of the molecules directly or indirectly involved in maintaining structurally intact the tumor fragment shed from the primary lesion." (PMID 37345079, 2023). "Similarly to sunitinib, cabozantinib inhibits the tyrosine kinase enzymatic activities of multiple receptors including VEGFR2, MET, AXL, and RET, which have been implicated in tumor proliferation, survival and neoangiogenesis." (PMID 37752423, 2023). "In conclusion, COMT may act as tumor suppressor in ER dependent BC not only by detoxification of catechol estrogens but also by suppressing cell invasion and interplay with MET pathway." (PMID 36690660, 2023). "A previous study showed that activation of the EMT program arises in tumor tissues of erlotinib-resistant patients without other resistance mechanisms, such as T790M mutation, c-MET, and Her-2 gene amplification." (PMID 37239162, 2023). "c-MET is the main target of the anti-tumor activity of cabozantinib." (PMID 36891274, 2023). "The MET pathway is also involved in tumor growth and metastasis progression in osteosarcoma." (PMID 37547755, 2023). "Moreover, recent evidence indicates that MET signaling participates in the acquirement of mesenchymal phenotype, tumor plasticity and adaptive responses to metabolic stress, contributing to the recurrence and metastatic dissemination of cancer cells." (PMID 36839989, 2023). "In addition to NGS, an immunohistochemistry (IHC)-based approach was undertaken in patients with sufficient remaining tumor samples (n = 20) to explore the association of EGFR and MET expression with tumor response." (PMID 37710001, 2023). "PDGF and MET signaling factors related to angiogenesis in tumor tissues were also enriched." (PMID 37580380, 2023).
tumor (continued). "Although the delivery of cancer cells via the vascular system does not fully recapitulate all the steps defining the process of dissemination from the primary tumor site to distant loci, this approach provides evidence for the essential role of MET signaling in pulmonary tissue colonization." (PMID 37345079, 2023). "In this context, MET represents an attractive molecular target in this tumor type." (PMID 37887325, 2023). "Subgroup analysis was conducted to evaluate the association of c-MET and SOX2 with the tumor stage, which showed that the odds of early-stage presentation in SOX2 immuno-positive cases are 75% lower compared to immuno-negative cases (OR = 0.25; 95% CI 0.14–0.45, p < 0.00001, I2 = 0%)." (PMID 37109090, 2023). "At recurrence, c-MET expression was assessed in available tumor samples." (PMID 38132404, 2023). "Our recent study indicated that LRIG3 can suppress the growth of GBM cell lines and tumor xenografts in Cell line-derived xenograft model by downregulating the activity of MET/phosphatidylinositol 3-kinase/Akt signaling pathway, thus playing an anti-tumor role in glioma." (PMID 36639372, 2023). "Accordingly, MET inhibition reduces tumor size and impedes metastases in rodent models." (PMID 37760640, 2023). "Complementary studies exploring the efficacy of combination therapy either in immunodeficient mice or in mice carrying tumors with disrupted Met gene expression confirmed that synergy requires at least two components, first, expression of MET in the tumor, second, a functional immune system." (PMID 36915128, 2023). "Thus, the mean volume of tumours formed by cells expressing METex14 was significantly higher than the volume of MET WT tumours (P < 0.01), indicating that exon 14 splicing drives MET oncogenicity in KI‐huHGF mice." (PMID 36799689, 2023). "MET genetic alterations might dominate the majority of tumor cells and dictate drug sensitivity; however, minor subclones harboring other mutations that confer resistance to MET blockade may coexist and be positively selected under drug pressure." (PMID 37760640, 2023). "Likewise, an antibody targeting the MET PSI domain hampered MET signalling in vitro and reduced tumor growth in preclinical models." (PMID 36293286, 2022). "This study found that enhanced expression of c-MET and HGF/SF may be associated with an increased risk for metastasis and tumor recurrence in this patient population." (PMID 36034555, 2022). "Alterations in HER2 and MET could be a target for anti-tumor drugs or lead to resistance to anti-EGFR therapeutics." (PMID 35326608, 2022). "MET is a proto-oncogene and has been found to be critical in tumor regulation." (PMID 36341343, 2022). "In two HCC patient cohorts (cohort I, n = 260; cohort II, n = 280), ETV1 expression was correlated with PTK2 and c-MET expression, and elevated expression of PTK2 or c-MET was associated with poor tumor differentiation, microvascular invasion, loss of encapsulation, and advanced TNM stage." (PMID 36109787, 2022). "However, the major obstacles of MET-targeted therapy are poor drug solubility and off-tumor effects, even oral high-dosing regimens cannot significantly increase the therapeutic drug concentration in primary and metastatic NSCLC." (PMID 36457016, 2022). "The current study developed highly internalizable anti-c-MET antibody Fab fusion proteins with intracellular epitope peptide chimera to achieve the dual intervention from the extracellular to intracellular targets in tumor therapy." (PMID 36233320, 2022). "Worse outcomes from bevacizumab, though not significant, were observed in patients whose tumours manifested both c-MET/VEGFR-2 co-localisation and VEGFR-2 rs2305945 G/G variant." (PMID 35144591, 2022). "Furthermore, treatment of GBM xenografts with chimeric U1/ribozymes targeting HGF and c-MET mRNA sensitized tumors to gamma radiation, and greatly improved tumor regression and cure rate." (PMID 36034555, 2022).